ABCA8 (ATP binding cassette subfamily A member 8)
Description:
[Isoform 1]: Catalyzes ATP-dependent import of organic anions such as taurocholate and estrone sulfate. In vitro, also imports ochratoxin A. Also mediates cholesterol efflux independent of apolipoprotein, and plays a role in sphingomyelin production in oligodendrocytes. [Isoform 3]: Catalyzes ATP-dependent efflux of cholesterol and taurocholate. Interaction with ABCA1 potentiates cholesterol efflux to lipid-free APOA1, which regulates high-density lipoprotein cholesterol levels.
Synonyms: KIAA0822
Tractability: Antibody: UniProt places it where antibodies can reach, with high confidence; its Gene Ontology location is reachable by antibodies, with high confidence; UniProt predicts a signal peptide or a membrane-spanning region. PROTAC: ubiquitination databases record sites on it; its protein half-life has been measured.
Gene: Protein-coding gene on chromosome 17 (68,866,052 to 68,955,470, reverse strand). Ensembl gene ENSG00000141338.
Subcellular location: Cell membrane; Basolateral cell membrane
Subcellular location (Human Protein Atlas): Nucleoplasm; Cytosol
Pathways (Reactome):
Transport of small molecules: ABC-family protein mediated transport
Gene Ontology:
Molecular function: ABC-type xenobiotic transporter activity; ABC-type transporter activity; ATPase-coupled transmembrane transporter activity; ATP binding; ATP hydrolysis activity
Biological process: positive regulation of cholesterol efflux; regulation of cholesterol efflux; sphingomyelin biosynthetic process; xenobiotic transmembrane transport; xenobiotic transport; cholesterol efflux; cholesterol transport; transmembrane transport; lipid transport
Cellular component: endoplasmic reticulum; plasma membrane; basolateral plasma membrane; membrane
Genetic constraint (gnomAD): Loss-of-function variants: 136 observed, 144.38 expected, observed/expected ratio (o/e) 0.94, 90% interval 0.82 to 1.09. The upper end of that interval is the gene's LOEUF score, 1.09, which puts it in group 4 of 6, group 1 being the genes least tolerant of losing a copy. Missense variants: 1,583 observed, 1,642.7 expected, observed/expected ratio (o/e) 0.96, 90% interval 0.92 to 1. Synonymous variants: 554 observed, 605.64 expected, observed/expected ratio (o/e) 0.91, 90% interval 0.85 to 0.98.
Homologues: Orthologues: chimpanzee ABCA8 (99% identical), macaque ABCA8 (97% identical), pig ABCA8 (80% identical), dog ABCA8 (77% identical), mouse Abca8b (76% identical), rat Abca8 (72% identical), rabbit ABCA8 (72% identical), zebrafish abca5 (43% identical), Caenorhabditis elegans abt-4 (23% identical), Drosophila melanogaster Abca3 (23% identical), Caenorhabditis elegans abt-2 (22% identical), Drosophila melanogaster CG6052 (21% identical), and 9 more. Paralogues in human: ABCA9 (72% identical), ABCA6 (59% identical), ABCA10 (58% identical), ABCA5 (42% identical), ABCA1 (26% identical), ABCA7 (26% identical), ABCA2 (26% identical), ABCA4 (26% identical), ABCA3 (25% identical), ABCA12 (25% identical), ABCA13 (24% identical).
Diseases named in the same sentence as ABCA8 in open-access papers:
ABCA8 is named in the same sentence as 32 diseases in open-access papers, as found by Europe PMC text mining. Sharing a sentence is not in itself a finding about the gene and the disease. The quoted sentences say what the papers report.
breast carcinoma (8 papers, 2018 to 2025). "Many genes such as ABCA8, MFAP4 and MAMDC2 also been potential diagnostic and prognostic biomarkers in hepatocellular carcinoma, breast cancer and ovarian cancer." (PMID 37563710, 2023). "Interestingly, in patients with breast cancer, the reduced ABCA8 expression lowers 5-year patients survival rate, is present in older patients (>60 age) as well as in the three breast cancer subtypes: ER-negative, PR-negative, HER-positive." (PMID 40724805, 2025). "Conversely, genes on chromosome 17 region “Nikolsky Breast Cancer 17q21-q25” were amplified in CR and contained ATP-binding cassette (ABC) transporters (ABCA5/ABCA6/ABCA8/ABCA9/ABCA10) among them (172 genes total, FDR = 7.39E−178)." (PMID 37012431, 2023). "LC–MS/MS results showed a reduction in the protein levels of ABCA8, ABCB1, and ABCG2; hence, we examined whether sulbactam can inhibit the mRNA expression of ABC transporters in the human breast cancer cells in the presence of doxorubicin." (PMID 30202239, 2018). "The role of the ATP-binding cassette (ABC) transporters in tumorigenesis of White breast cancer patients is further supported by the enrichment of the “brown” module in basal transcription factors, including the ATP-binding cassette subfamily members ABCA9, ABCC9, ABCG2, ABCB1, ABCA6, and ABCA8." (PMID 32873298, 2020).
pancreatic cancer (7 papers, 2021 to 2025). "Members of the ABCB, ABCC, and ABCG families are well-established mediators of therapy resistance, and recent studies have also implicated ABCA6 and ABCA8 in drug resistance in pancreatic cancer." (PMID 41515995, 2025). "Emerging evidence supports a role for the ABCA subfamily in chemoresistance, with GH upregulating ABCA6 and ABCA8 in pancreatic cancer." (PMID 40806252, 2025). "In pancreatic cancer, ABCG2, ABCC1, ABCC5, and ABCA8 have been specifically reported to be associated with gemcitabine resistance, whereas additional ABC transporters are widely expressed in chemoresistant PDAC cells." (PMID 39000545, 2024). "In BRCA1-proficient cells, for instance, the activity of BCRP and MRP1/2 decreased, whereas a strong increase in ABCA8 transcription was observed, which has already been described in the context of MDR in pancreatic cancer." (PMID 37568590, 2023).
hepatocellular carcinoma (6 papers, 2020 to 2025). A malignant tumor that arises from hepatocytes. "One study reported that in a subset of hepatocellular carcinoma human patients, ABCA8 and ABCA9 downregulation was significantly associated with shorter survival time." (PMID 40320296, 2025). "ABCA8 is mostly downregulated in different types of cancers, including hepatocellular carcinoma, prostate cancer, ovarian cancer, and tongue squamous cell carcinoma." (PMID 32685482, 2020). "ABCA8 inhibits proliferation and metastasis of hepatocellular carcinoma." (PMID 35460704, 2022). "However, the overexpression of ABCA8 has been found to be correlated with the favorable prognosis of patients with hepatocellular carcinoma." (PMID 32685482, 2020). "The expression of ABCA8 in human hepatocellular carcinoma (HCC) tissues and cell lines was examined using qPCR, immunoblotting, and immunohistochemical staining." (PMID 32430024, 2020). "Namely, downregulated expression of ABCA8 induced epithelial transformation to mesenchyme via the ABCA8/ERK/ZEB1 pathway and promoted the progression of hepatocellular carcinoma." (PMID 41465541, 2025).
ovarian carcinoma (4 papers, 2016 to 2023). A malignant neoplasm originating from the surface ovarian epithelium. "ABCA8 has also been studied by others in relation to cancer and it has been found to be downregulated in multidrug resistant ovarian cancer cell lines as well as in breast and prostate cancer." (PMID 29324814, 2018). "ABCA8 is responsible for the transport of a variety of inflammatory mediators and lipids that have direct relevance to tumor progression in ovarian cancer." (PMID 27220887, 2016).
medulloblastoma (3 papers, 2013 to 2023). A malignant, invasive embryonal neoplasm arising from the cerebellum. "In one study, ABCA8 was found to be upregulated in a subtype of medulloblastoma defined as Sonic hedgehog (SHH) and downregulated in the subtype defined as Wnt signaling." (PMID 29324814, 2018).
prostate carcinoma (3 papers, 2018 to 2022). A carcinoma that arises from epithelial cells of the prostate gland. "For example, eight ABC transporter genes (e.g., ABCA8, ABCC6, and ABCC9) were significantly downregulated in prostate cancer tissues compared with noncancerous tissues." (PMID 35280774, 2022).
Fibroadenoma (2 papers, 2016 to 2020). A benign tumor of the breast characterized by the presence of stromal and epithelial elements. "Using machine learning to build predictive regression models, we selected a five-gene transcript set (ABCA8, APOD, CCL19, FN1, and PRAME) to discriminate between fibroadenomas and phyllodes tumors." (PMID 26961242, 2016).
lung carcinoma (2 papers, 2011 to 2022). "Our microarray analysis results and preliminary lung tissue array study demonstrated that the ABC gene signature, consisting of ABCA4 and ABCA8 together with ABCC3, can discriminate lung AC vs AT and be considering as a novel lung cancer diagnostic biomarker (not published)." (PMID 22369099, 2011).
Stomach Adenocarcinoma (2 papers, 2020 to 2022). "ABCA8 expression was downregulated in stomach adenocarcinoma and was positively associated with six types of infiltrated immune cells, particularly M2 macrophages." (PMID 35837087, 2022).
breast tumours (1 paper, 2022). "Nevertheless, the genes ABCA3, ABCA8, ABCA12, ABCC7, and ABCC8 cluster in breast tumours, and the expression of this gene group was associated with the clinical and pathological parameters of tumours." (PMID 35631534, 2022).
colorectal cancer (1 paper, 2022). A primary or metastatic malignant neoplasm that affects the colon or rectum. "ABCA5 and ABCA8 were lowly expressed in cancer tissues, and ABCC1 was highly expressed in colorectal cancer tissues." (PMID 35783152, 2022).
melanoma (1 paper, 2016). A malignant, usually aggressive tumor composed of atypical, neoplastic melanocytes. "APOD (apolipoprotein D) and ABCA8 (ATP-binding cassette, sub-family A member 8) encode transporter proteins while PRAME (preferentially expressed antigen in melanoma) and CCL19 (chemokine ligand 19) genes are involved in immunoregulatory processes." (PMID 26961242, 2016).
rectal cancer (1 paper, 2022). A primary or metastatic malignant neoplasm that affects the rectum. "The survival analysis of ABCA5, ABCA8, and ABCC1 genes was performed in the TCGA colon and rectal cancer (TCGA-COADREAD) and GSE24551-GPL5175 datasets." (PMID 35783152, 2022).
schizophrenia (1 paper, 2021). A major psychotic disorder characterized by abnormalities in the perception or expression of reality. "The ABCA8 gene is important for lipid metabolism in oligodendrocytes, myelin formation and maintenance, and ABCA13 from the same subfamily is associated to schizophrenia through GWAS." (PMID 33892787, 2021).
stomach cancer (1 paper, 2024). "By multimodal analysis, we found a link between the ECM proteins enriched in malignant subtype (PCC-NOS) and a particular type of cell found in tumors, ABCA8+ fibroblast, which is related to worse outcomes in stomach cancer patients." (PMID 39305996, 2024).
thyroid cancer (1 paper, 2023). "ABCA8 and ABCA12 are considered hallmark ABC transporters, which may be involved in the regulation of immune cell infiltration in thyroid cancer." (PMID 37563740, 2023).
urinary bladder cancer (1 paper, 2023). A primary or metastatic malignant neoplasm involving the bladder. "The roles of ABCC5, ABCA8, ABCC10, ABCB10, ABCG1, ATP7B, ABCG2, and mitochondrial SLC25A10 in platinum-receiving urinary bladder cancer patients should be the subject of further investigation." (PMID 36650399, 2023).
cancer (17 papers, 2010 to 2025). A tumor composed of atypical neoplastic, often pleomorphic cells that invade other tissues. "Only a few studies have linked ABCA8 to chemosensitivity in human cancers." (PMID 33431858, 2021). "However, the functional roles of ABCA8 and its underlying mechanisms in regulating the chemosensitivity of human cancer remain unknown." (PMID 33431858, 2021). "Regarding ABCA8, the increased expression of this ABCA subfamily transporter has been linked to poor prognosis of cancer patients." (PMID 33431858, 2021). "This is the first time the potential mechanism (inducing EMT in HCC) of ABCA8 in cancer has been revealed." (PMID 32430024, 2020). "ABCA8, a member of the superfamily of ATP-binding cassette transporters, plays a critical role in cancer biology and drug resistance." (PMID 32685482, 2020). "High expression of ABCA8 in various cancers has been reported to be correlated with poor prognosis." (PMID 32685482, 2020). "Our study is the first to elucidate the role of ABCA8 in cancer, particularly in HCC." (PMID 32430024, 2020). "However, the mechanism of ABCA8 in the process of cancer activation is still ambiguous." (PMID 32430024, 2020). "In contrast, the 176 passager genes were biased toward functions developed with cancer progress, such as their top genes, SCN4B and SLIT3, which controlled cancer cell migration, and the ABCA8 gene that related to cancer chemoresistance." (PMID 38666214, 2024). "Our work is the first to elucidate the role of ABCA8 in cancer, particularly in HCC, and ABCA8 is expected to be a new therapeutic target for HCC." (PMID 32430024, 2020). "We identified 15 highly connected hub genes in MEtan, including ABCA8, AFP, EGR3, EXO1, HMGA1, MT1X and VARS, which play roles as major regulators in cell-cycle regulation and cancer development." (PMID 27220887, 2016). "In contrast, DCN (chr12q21.33), LIFR (chr5p13.1), ABCA8 (chr17q24.2), C7 (chr5p13.1) and ZEB2 (chr2q22.3) on predicted PCSRs were down-expressed in 9, 7, 8, 8 and 8 cancers, respectively." (PMID 24796549, 2014). "Some selected genes with high discriminative ability, belonging to three cancer-relevant pathways, such as ATP-binding cassette (ABC) family of genes (ABCA4, ABCA8) were identified as prospective gene markers of lung AC other one (ABCB1, ABCC3 and ABCF2) should be also under serious consideration." (PMID 22369099, 2011). "Furthermore, ABCA8 expression was primarily noted in the stromal region, not in cancer cells, reinforcing the specificity of ABCA8-positive fibroblasts to the PCC-NOS subtype." (PMID 39305996, 2024). "Although ABCA8 is a DEG with survival correlation, its connection was not coordinative with survival rates, as it suggests higher expression in cancer than normal while indicating better prognosis, the gene was eliminated." (PMID 34124056, 2021). "We further confirmed that ABCA8 and FABP4 expression were significantly decreased in STAD tissues, regardless of clinical characteristics, such as cancer stage, grade, and nodal metastasis status of STAD." (PMID 32685482, 2020).
tumor (15 papers, 2009 to 2025). "The C1 ABCA8+ subtype exhibits increased proliferative activity and is implicated in tumor growth and metastasis." (PMID 41514658, 2025). "Low expression of ABCA8 was associated with increased tumor size, metastasis, and a more advanced TNM stage." (PMID 32430024, 2020). "The study proposed and validated a NEFH+ tumor cell–PTN–NCL–CAFs conversion axis in PCa, underscoring the central role of the C1 ABCA8+ subtype in tumor progression." (PMID 41514658, 2025). "With IHC analysis of the tumor microarray, we identified the grade of ABCA8 protein expression with the tumor tissue of 114 GC patients." (PMID 39305996, 2024). "Using tumor microarray analysis, we confirmed the CAFadi surface marker, ATP binding cassette subfamily A member 8 (ABCA8), predominantly present in PCC-NOS tumors." (PMID 39305996, 2024). "Six diagnostic genes were mutated in descending frequency in the tumor group: COL4A1, ABCA8, MAMDC2, FAP, TMEM100, and LY6E." (PMID 36685898, 2022). "COL4A1, COL6A3, FAP, and LY6E were up-regulated in the tumor group in the training set, whereas ABCA8, MAMDC2, TMEM100, and TMEM266 were down-regulated." (PMID 36685898, 2022). "The tumor inhibition rate was decreased from 73.3% in control tumors to 45.5% in ABCA8-overexpressing tumors, suggesting that increased ABCA8 expression reduced the sensitivity of human PC cells to GEM therapy." (PMID 33431858, 2021). "The tumor inhibition rate of GEM therapy for Gem-R tumors was increased from 28.5% to 58.1% by ABCA8 knockdown." (PMID 33431858, 2021). "Decreased ABCA8 expression in HCC was positively correlated to tumor diameter (p = 0.0121), metastasis (p = 0.0103) and TNM stage (p = 0.0106)." (PMID 32430024, 2020). "Consistent with the characteristics of clinical cases, we found that ABCA8 can inhibit the proliferation, invasion, and migration of tumor cells in vivo and in vitro." (PMID 32430024, 2020). "The results indicated that ABCA8 and FABP4 were negatively correlated with tumor purity and were positively associated with six types of immune cells." (PMID 32685482, 2020). "In short, our results showed that ABCA8 has a tumor inhibition effect both in vitro and in vivo." (PMID 32430024, 2020). "The ABCA8 is a tumor suppressor gene whose downregulation transforms epithelium into mesenchyme, via the ERK/ZEB1 signaling pathway, promoting tumor progression." (PMID 36703136, 2023). "Our evidence shows that the expression of ABCA8 is significantly decreased in HCC tissues and HCC cell lines when compared to adjacent non-tumor tissues and normal liver cells." (PMID 32430024, 2020). "These lipid-enriched CAFs, characterized by co-expression of ATP-binding cassette subfamily A member 8 (ABCA8) and fibroblast activation protein (FAP) (ABCA8+FAP+), promote tumor metabolism through ABCA8-mediated lipid transfer to fuel mitochondrial oxidative phosphorylation (OXPHOS)." (PMID 40861469, 2025). "Whereas GEM treatment exhibited a profound inhibitory effect on the growth of control tumors (tumor weight: 0.30 ± 0.07 g vs. 0.07 ± 0.05 g, P < 0.001), it failed to achieve comparable therapeutic efficacy for ABCA8-overexpressing tumors (tumor weight: 0.36 ± 0.12 g vs. 0.20 ± 0.07 g, P < 0.05)." (PMID 33431858, 2021).
neurodegenerative disease (1 paper, 2022). A disorder of the central nervous system characterized by gradual and progressive loss of neural tissue and neurologic function. "Apart from the promotion of lipid transport in the brain, the function of this protein in the central nervous system is still not well known, and further exploration of the role of Abca8 in neurodegenerative diseases is needed." (PMID 35335269, 2022).
ABCA8 also shares sentences with these, for which no sentence is quoted: brain tumors (1 paper); Cirrhosis (1); colon cancer (1); endometrial cancer (1); gingival hyperplasia (1); invasive ductal breast carcinoma (1); liver cancer (1); malignant mesothelioma (1); metastatic tumors (1); phyllodes tumor (1); renal cell carcinoma (1); tongue squamous cell carcinoma (1).